CX3CR1 (C-X3-C motif chemokine receptor 1)
Diseases named in the same sentence as CX3CR1 in open-access papers (continued):
Sharing a sentence is not in itself a finding about the gene and the disease.
Obesity (39 papers, 2015 to 2025). Accumulation of substantial excess body fat. "For example, microglial CX3CR1 (C-X3-C motif chemokine ligand 1) signalling determine obesity susceptibility in mice and its deficiency induces inflammation and insulin resistance in adipose tissue." (PMID 38483771, 2024). "CCL2 (C-C Motif Chemokine Ligand 2) was down-regulated in the ICU patients as was CX3CR1 (C-X3-C Motif Chemokine Receptor 1), which is associated with obesity, a risk factor for severe influenza disease." (PMID 39192977, 2024). "Conversely, sympathetic neuron-associated macrophages (Cx3cr1+ SAMs) that are recruited to the nerve bundles of WAT during obesity can degrade norepinephrine, which is otherwise crucial for lipolysis and thermogenesis." (PMID 35211733, 2022). "Fractalkine (FKN), which is crucial in the neuron-microglial crosstalk via the activation of microglial CX3CR1, has been implicated in the development of hypothalamic inflammation in obesity." (PMID 36210435, 2022). "Partial knockdown of CX3CR1 or annexin V-treatment both attenuate obesity-associated cognitive decline by preventing microglial activation and phagocytosis, respectively." (PMID 34201844, 2021). "For instance, CX3CR1 deficient mice were protected against the development of HFD-induced obesity and WAT inflammation." (PMID 34948325, 2021). "This places more emphasis on finding a therapeutic means to prevent NK cell trafficking to the omentum in obesity-associated cancer and our data suggest that CX3CR1 antagonism provides the solution." (PMID 35008227, 2021). "Strengthening this point, female CX3CR1 KO mice phenocopied “male-like” microglial activation and increased their susceptibility to diet-induced obesity." (PMID 33374371, 2020). "Here, the authors reveal sex-specific regulation of hypothalamic microglial activation through CX3CR1 signalling, providing a potential mechanism for differential susceptibility to diet-induced obesity." (PMID 28223698, 2017). "The fractalkine (CX3CL1-CX3CR1) chemokine system is associated with obesity-related inflammation and type 2 diabetes, but data on effects of Cx3cr1 deficiency on metabolic pathways is contradictory." (PMID 26393344, 2015). "Using a novel ex vivo approach to simultaneously expose NK cells to two key competing tissue compartments in obesity-associated cancer patients, we have shown that blocking CX3CR1 limits fractalkine-mediated NK cell migration towards the soluble chemotactic cues of the omentum but not the tumour." (PMID 38369570, 2024). "Female mice with Cx3Cr1 knockout develop “male” accumulation and activation of microglia in the hypothalamus, which is accompanied by a noticeable increase in their predisposition to obesity caused by diet." (PMID 36831738, 2023). "Of considerable interest for the present study is the possibility that CX3CR1 activation may be a promising way to reduce body weight and improve brain inflammation associated with obesity." (PMID 35871167, 2022). "Similarly, polymorphisms of the fractalkine receptor gene (CX3CR1) have been associated with asthma, atopy, and obesity." (PMID 33396413, 2020). "Thus, microglial CX3CR1 signalling represents a molecular switch that toggles the degree of obesity susceptibility in a sex-specific manner." (PMID 28223698, 2017). "Female Cx3cr1 knockout mice develop ‘male-like' hypothalamic microglial accumulation and activation, accompanied by a marked increase in their susceptibility to diet-induced obesity." (PMID 28223698, 2017). "Polymorphisms in the CX3CR1 gene have also been associated with obesity and metabolic traits." (PMID 26393344, 2015). "Additionally, function of CX3CR1 in MAFLD may confused now, as CX3CR1 knockout mice exhibit increased susceptibility to high-fat diet-induced obesity, insulin resistance, hepatic degeneration, and inflammation." (PMID 40918148, 2025).
Obesity (continued). "Therefore, we examined whether fractalkine-CX3CR1 signalling involved in regulating food intake and hypothalamic inflammation associated with obesity pathogenesis." (PMID 35871167, 2022). "Importantly, pre-treatment with a CX3CR1 antagonist can help rescue this migration, further indicating the central role that fractalkine plays in NK cell phenotype, function and migration in obesity-associated cancer." (PMID 35008227, 2021). "Thus, to gain more insight into the role of Gr1low monocytes during obesity, we used female mice models, which are associated with major changes in the proportion of Gr1low monocytes in blood: CX3CR1−/− mice; CD11c-hBcl2 mice; and the double genetically modified CX3CR1−/−/CD11c-hBcl2 mice." (PMID 28769122, 2017). "Interestingly, the sex-specific microglial responses to high-fat diet feeding in mice are also mediated by Cx3cr1 signaling, whereas Cx3cr1 knockout female mice developed ‘male-like’ hypothalamic microglial accumulation and activation with increased susceptibility to diet-induced obesity." (PMID 39975913, 2025). "In females, the increase in CX3CR1 signaling triggered by HFD protects against diet-induced obesity by reducing microglial activation." (PMID 39302596, 2024). "An upregulation of CX3CR1 in monocyte subpopulations from patients with obesity was also shown in a previous study." (PMID 38175171, 2024). "We studied the distribution of the CD14/CD16 monocyte subsets as well as their CX3CR1 expression patterns in whole-blood measurements from 92 patients with obesity and/or OSAS with regard to plasma CXCL10 values and individual clinical parameters." (PMID 38175171, 2024). "Our data show, for the first time, to our knowledge, that CX3CR1 is involved in alternative CXCL10 signaling in human monocytes in obesity-related inflammation." (PMID 38175171, 2024). "We have shown significant correlations between plasma MIF and CX3CR1 expression on all three monocyte subsets in patients with obesity." (PMID 38175171, 2024). "It has been found that knockdown of IL‐1R1‐expressing CX3CR1+ cells in mice with dietary obesity can eliminate the cognition and restore the immunoquiescence of microglia in hippocampus, proving the pivotal role of neuroinflammation." (PMID 34951130, 2022). "We used transgenic female mouse models allowing the modulation of circulating Gr1low monocyte number (decreased number in CX3CR1−/− mice and increased number in CD11c-hBcl2 mice) and studied obesity upon HFD." (PMID 28769122, 2017). "Further investigations on primary monocyte subsets in larger cohorts in correlation with adipose tissue-infiltrating macrophages are needed to unravel the impact of monocytic CXCL10/CX3CR1/MIF signaling on obesity-related systemic inflammation and its concomitant diseases." (PMID 38175171, 2024). "Furthermore, surface expression of CX3CR1 was measured and revealed significantly increased CX3CR1 expression levels on CMs (p = 0.0205) and NCMs (p = 0.0223) from patients with obesity compared with healthy donors." (PMID 38175171, 2024). "In the absence of circulating estrogens in vitro, female but not male neurons were shown to utilize lipids as a pro-survival fuel source, and in a separate study, it was shown that female microglia support protection from diet-induced obesity by an estrogen-independent increase in CX3CR1 signaling." (PMID 37731609, 2023). "Our study provides that fractalkine-CX3CR1 signalling may be an attractive target for the pharmacological treatment of obesity." (PMID 35871167, 2022). "Norepinephrine degradation has been reported as a key function of SAMs in adipose, which also express the Cx3cr1 marker and are recruited to adipose in obesity, and may represent a subset of adipose neuroimmune cell phenotypes." (PMID 35795142, 2022). "Recent studies found sex differences exist in microglial CX3CR1 signaling in amouse obesity model." (PMID 29692197, 2018).
Obesity (continued). "However, different models of Cx3cr1 knockout mice resulted in variable results on diet induced obesity." (PMID 27623010, 2016). "However, the regulation of inflammatory genes seemed to be restricted to a small number of genes (for example, CX3CR1 and IL1B), as most genes associated with inflammation remained unchanged, indicating an overall subtle inflammatory response during obesity in humans." (PMID 37414931, 2023). "CCR2 and CX3CR1 may synergistically impact the inflammatory monocyte phenotypes in obesity." (PMID 35422759, 2022). "To explain the link between the absence of hypothalamic microglial activation and relative protection from DIO observed in female mice, we hypothesized that intact CX3CR1 signalling in females during HFD feeding limits microglial reactivity and reduces obesity susceptibility." (PMID 28223698, 2017). "Induced UCB-derived microglia-like cells (iMGL) expressed higher levels of activation markers CD163, CX3CR1, TMEM119, and HLA-DR but reduced phagocytic capacity with maternal pregravid obesity." (PMID 39872537, 2024). "Here, using a model of microglia derived from UCBMC in vitro (iMGL), we report an increase in the expression of activation markers (CD163, CX3CR1, TMEM119, HLA-DR) with pregravid obesity, while phagocytic capacity was reduced." (PMID 39872537, 2024). "The expression of chemokine receptor CX3CR1 was significantly higher on classical monocytes from normal weight OSAS patients (p = 0.0029) and patients with obesity (p = 0.0029) as compared to healthy donors." (PMID 38172514, 2024). "Our data revealed increased expression levels of CD11a (integrin-α L; LFA-1), CD11b (integrin-α M; Mac-1), and CX3CR1 (CX3CL1 receptor) and decreased expression of CD29 (integrin β-1) on certain monocyte subsets in patients with obesity." (PMID 36921085, 2023). "The present study demonstrated that fractalkine suppresses food intake via activation of the BDNF-TrkB pathway and that reduction of fractalkine-CX3CR1 signalling exacerbates HFD-induced hypothalamic inflammation and accelerates obesity in HFD-fed mice." (PMID 35871167, 2022). "However, the Cx3cr1+ macrophages are reportedly IL27 producers, where administration of IL27 protects against IR and obesity through its direct actions on Ucp1high adipocytes." (PMID 35211733, 2022). "CX3CR1 is also expressed in subsets of peripheral monocytes and macrophages so it is possible that circulating myeloid cells that infiltrate the MBH in HFD-fed mice may also contribute to the anti-obesity effect of CX3CL1." (PMID 35742824, 2022). "The authors used a series of dietary obesity and VAT transplantation experiments using Nlrp3−/− mutant mice and Tg mice with inducible deletion of IL1r1 (interleukin 1 receptor type 1) in CX3CR1(CX3C chemokine receptor 1)-expressing cells to verify their hypothesis." (PMID 34070553, 2021). "Analysis of monocytic adhesion molecules revealed elevated expression levels of CD11a and CX3CR1 in response to both disease conditions, whereas CD11b was elevated in patients with OSAS and patients with OSAS and obesity but not in the obesity cohort." (PMID 38172514, 2024).
breast carcinoma (37 papers, 2011 to 2025). "Recently, IL-17+ γδ T cells have been shown to promote resistance to CDK4/6 inhibitors in hormone receptor (HR)+ breast cancer, at least in part by favoring the repolarization of tumor-associated macrophages (TAMs) toward an immunosuppressive CX3CR1+ phenotype." (PMID 40859036, 2025). "In summary, our data delineate a novel immunological mechanism through which γδ T cells recruited to the TME of HR+HER2− mammary tumors upon CCL2 secretion as driven by CDK4/6 inhibitors promote the IL17-dependent repolarization of TAMs toward a CX3CR1+ profile associated with resistance to therapy." (PMID 40662849, 2025). "Therefore, interfering with the pairing of CX3CR1 with FKN, through the deletion of CX3CR1, can drastically limit the capability of breast cancer circulating tumor cells to disseminate and cause secondary tumors, particularly in the bones." (PMID 34066014, 2021). "In addition, CX3CR1 has been implicated in metastasis of prostate cancer cells and breast cancer cells to bone, and CXCR4 may have a particular role in bone metastasis." (PMID 29088715, 2017). "Specifically, CX3CR1 can be detected on both healthy and malignant breast epithelial cells, with a greater percentage of cells expressing high levels of CX3CR1 in breast cancer tissues and even higher expression in bone metastases." (PMID 37025604, 2023). "A related study on breast cancer metastasis shows that CX3CR1-mediated resident microglia migration promotes brain metastasis in the mouse models where resident microglia are the major immune population." (PMID 37149684, 2023). "Breast cancer cells intracardially injected in total CX3CR1 KO mice had reduced bone metastases compared to wildtype mice, and bone metastases in wildtype mice were reduced with CX3CR1 antagonist treatment." (PMID 37025604, 2023). "In BRCA (breast carcinoma) and LUAD (lung adenocarcinoma), higher CX3CR1 expression was associated with a higher M2 macrophage fraction but a lower M1 macrophage fraction." (PMID 37771579, 2023). "A small molecule antagonist to CX3CR1 has shown efficacy in preclinical models of breast cancer; however, a challenge of small molecule CX3CR1 antagonists is that they can target several related GPCRs (G Protein-coupled receptors) and are not unique to CX3CR1." (PMID 37771579, 2023). "In breast cancer, CX3CR1 expression correlates with brain metastasis 138, and CX3CR1 is also expressed within spinal metastases and acts through the Src/FAK signaling axis to promote migration and invasion." (PMID 36118530, 2022). "When breast cancer cells are injected into the left ventricle of mice, CX3CR1 drives cancer cells to the skeleton through interactions with CX3CL1 expressed by bone marrow endothelial cells." (PMID 36118530, 2022). "In contrast, other studies reported about prostate and breast cancer showed that the CX3CR1-positive tumor cells were circulating in the blood, attracted at distant sites by some ligand-expressing cells." (PMID 35478937, 2022). "Comparable results were obtained from FKN knockout transgenic mice (also grafted with MDA-MB-231) indicating that CX3CR1 is directly involved in the lodging of breast cancer cells to the bone." (PMID 34066014, 2021). "High levels of CX3CL1 in cells can attract those cancer cells expressing its receptor CX3CR1 and trigger them to invade the tissue and form metastases as seen e.g. in breast cancer spinal metastases." (PMID 32321535, 2020). "More recently a novel small-molecule CX3CR1 antagonist was developed and tested in a preclinical breast cancer model showing an anti-bone metastatic effect." (PMID 30845779, 2019). "Fractalkine also plays a role in the dissemination of breast cancer cells to bone; and inhibiting the fractalkine receptor, CX3CR1, has been shown to reduce breast cancer cell bone dissemination and development of bone metastatic lesions." (PMID 29867053, 2018).
breast carcinoma (continued). "A novel small-molecule CX3CR1 antagonist has shown preclinical evidence of activity by interfering with progression and metastasis in a breast cancer model." (PMID 29190915, 2017). "Several experimental models have analyzed the influence of the CX3CR1/CX3CL1 axis in the biology of breast cancer and the possible therapeutic targeting of CX3CL1." (PMID 24799766, 2014). "For instance, it was shown that exposure to proinflammatory cytokines increased the expression of CX3CR1 on human breast cancer cells thereby enhancing migration of these cells toward CX3CL1." (PMID 23029290, 2012). "The goal of this study was to determine the role of fractalkine and its specific receptor CX3CR1 in the homing of circulating breast cancer cells to the skeleton." (PMID 21933397, 2011). "Here we show that both normal and malignant breast tissues express CX3CR1 and the ability of breast cancer cells to lodge in the skeleton of animal models is increased by the over-expression of CX3CR1." (PMID 21933397, 2011). "Similar transcriptional features could be documented in CX3CR1+ TAMs from human HR+HER2− breast cancer samples." (PMID 40662849, 2025). "CX3CR1 was more highly expressed in spinal metastases than para-tumor tissue in breast cancer." (PMID 38731899, 2024). "Duonco primarily targeted HER2 and CX3CR1, both frequently overexpressed in breast cancer." (PMID 39351063, 2024). "These cancers include frequently diagnosed cancers, such as colorectal cancer, breast cancer, and lung cancer, in which the absence or low expression of FKN/CX3CR1 in tumor tissue is a poor prognostic factor associated with an increased risk of metastatic progression." (PMID 38731899, 2024). "Last, CX3CL1/CX3CR1 play a role in bone metastasis of other cancers, including breast cancer." (PMID 37025604, 2023). "Similarly, increased CX3CR1 expression was correlated with bone metastasis in prostate cancer, similarly in breast cancer, expression of CX3CR1 predicted the occurrence of BM40,48." (PMID 37770496, 2023). "It has also been shown that CX3CR1 is involved in homing of breast cancer metastases to the brain." (PMID 23029290, 2012). "Finally, by using functional mutants of CX3CR1 we provide evidence that this receptor regulates both adhesion and extravasation of breast cancer cells." (PMID 21933397, 2011). "Finally, we conclusively confirmed the crucial role of CX3CR1 on breast cancer cells for both adhesion to bone marrow endothelium and extravasation into the bone stroma." (PMID 21933397, 2011). "Of note, repolarizing CX3CR1+ TAMs toward an immunostimulatory configuration with a monoclonal antibody targeting colony stimulating factor 1 receptor (CSF1R) ameliorated the activity of P+T against M/D-driven mammary carcinoma, to a magnitude similar to IL17A neutralization." (PMID 40662849, 2025). "Despite this and other unknowns, targeting TIM-3, IL-1β receptors, IL-17+ γδ T cells, IL-17 and their downstream immunological effectors (perhaps including CX3CR1+ TAMs) represent promising strategies to limit metastatic dissemination and resistance to therapy in multiple breast cancer subtypes." (PMID 40859036, 2025). "Notably, CX3CR1 promotes macrophage recruitment during mammary tumor formation." (PMID 34001208, 2021). "Specifically, in breast cancer, the chemokine receptors that exhibited the most significant correlations were CCR2, CCR4, CCR5, CCR6, CCR8, CXCR2, and CX3CR1." (PMID 40649753, 2025). "As for the CX3CR1 on CD14+ CD16- monocyte (p-value: 1.15×10−166), the IVW method clearly demonstrated a protective effect against ER- breast cancer." (PMID 38327747, 2024). "CRISPR deletion of CX3CR1 or its blockade in human tumor lines of PDAC, breast cancer, prostate cancer, bladder cancer and glioblastoma results in a decrease in the ability of tumor cells to migrate and metastasize." (PMID 37771579, 2023).